Y_RNA (Y RNA )
Gene: Miscellaneous RNA gene on chromosome 21 (6,365,955 to 6,366,055, forward strand). Ensembl gene ENSG00000276902.
Homologues: Orthologues: chimpanzee Y_RNA (97% identical), chimpanzee Y_RNA (88% identical), chimpanzee Y_RNA (87% identical). Paralogues in human: Y_RNA (100% identical), Y_RNA (86% identical), RNY3 (85% identical), Y_RNA (85% identical), RNY3P1 (84% identical), Y_RNA (84% identical), RNY3P11 (83% identical), Y_RNA (83% identical), Y_RNA (82% identical), Y_RNA (81% identical), RNY3P3 (80% identical), Y_RNA (80% identical), and 95 more.